LINC00574 (long independently transcribed non-coding RNA 574)
Synonyms: C6orf208; FLJ13162; dJ182D15.1; CRALA
Gene: Long non-coding RNA gene on chromosome 6 (169,790,036 to 169,890,808, forward strand). Ensembl gene ENSG00000231690.
Diseases named in the same sentence as LINC00574 in open-access papers:
LINC00574 is named in the same sentence as 2 diseases in open-access papers, as found by Europe PMC text mining. Sharing a sentence is not in itself a finding about the gene and the disease. The quoted sentences say what the papers report.
asthenozoospermia (1 paper, 2025). "The expression level of linc00574 was quite higher in patients with asthenozoospermia, and there was a positive correlation between TCTE3 and linc00574 expression levels." (PMID 40092557, 2025).
LINC00574 also shares sentences with these, for which no sentence is quoted: breast carcinoma (1 paper).